APRT (adenine phosphoribosyltransferase)
Diseases named in the same sentence as APRT in open-access papers:
APRT is named in the same sentence as 49 diseases in open-access papers, as found by Europe PMC text mining. Sharing a sentence is not in itself a finding about the gene and the disease. The quoted sentences say what the papers report.
kidney stones (12 papers, 2011 to 2025). "Among them, APRT deficiency can lead to serious kidney diseases, such as kidney stones, interstitial nephritis, and 2,8-Dihydroxyadenine (DHA) precipitation in renal interstitial failure." (PMID 40774030, 2025). "APRT deficiency must be suspected in all cases of nephrolithiasis in children, recurrent nephrolithiasis (particularly if the stones are radiolucent), and nephrolithiasis associated with unexplained kidney dysfunction." (PMID 40182129, 2025). "2,8-Dihydroxyadenine nephrolithiasis is the result of a metabolic abnormality due to the deficiency of the enzyme adenine phosphoribosyltransferase (APRT), it is not only promote stone formation, but also induced nephropathy." (PMID 38074799, 2023). "APRT deficiency seems to be an important determinant in patients with unexplained nephrolithiasis or crystalline nephropathy." (PMID 35635787, 2022). "Adenine phosphoribosyltransferase deficiency is a rare, autosomal recessive disorder of purine metabolism that causes nephrolithiasis and progressive chronic kidney disease." (PMID 33707627, 2021). "Uncommon hereditary diseases can also present with nephrolithiasis, such as primary hyperoxaluria, cystinuria, Dent’s disease, and adenine phosphoribosyltransferase (APRT) deficiency." (PMID 34576247, 2021). "These patients, with biallelic mutations in APRT, have adenine phosphoribosyltransferase deficiency and often develop recurrent nephrolithiasis." (PMID 32719990, 2020). "Adenine phosphoribosyl transferase (APRT) deficiency is a rare genetic form of kidney stones and/or kidney failure characterized by intratubular precipitation of 2,8 dihydroxyadenine crystals." (PMID 31752739, 2019). "Such crystals deposits in parenchyma are pathognomonic of a rare disease, adenine phosphoribosyltransferase deficiency, an inherited disease able to induce recurrent kidney stones and/or kidney failure." (PMID 22125652, 2011). "Adenine and xanthine are also converted to AMP and XMP but may cause kidney stones, as seen in xanthinuria and adenine phosphoribosyltransferase deficiency." (PMID 38960035, 2024). "Radiolucent kidney stones are the most common clinical manifestation, followed by chronic kidney disease which has already progressed to end-stage kidney disease in 15–20% of patients at the time of diagnosis of APRT deficiency." (PMID 33707627, 2021). "We note that we observe a strong association of a missense variant in the APRT gene encoding adenine phosphoribosyltransferase (rs104894506[A], NP_000476.1:p.Asp65Val, MAF=1.26%) with kidney stones under the recessive model (OR=31.97, P=6.83 × 10−10)." (PMID 26272126, 2015). "Adenine phosphoribosyltransferase (APRT) deficiency is a rare autosomal recessive disorder of the purine pathway that results in excessive production of 2,8-dihydroxyadenine and subsequent nephrolithiasis and crystal nephropathy." (PMID 41383865, 2025). "Therefore, APRT deficiency should be included in the differential diagnosis of crystalline nephropathy even with no history of nephrolithiasis, as a timely diagnosis has therapeutic implications." (PMID 35635787, 2022). "The study results showed that inclusion of genetic determination of APRT deficiency in the differential diagnosis of crystalline nephropathy, even in the absence of a history of nephrolithiasis, can improve renal outcomes and may improve allograft survival." (PMID 35635787, 2022).
primary hyperoxaluria (6 papers, 2011 to 2024). A hereditary disorder characterized by excessive oxalate production, leading to hyperoxaluria. "Increasing transplant physicians knowledge of APRT deficiency and primary hyperoxaluria should enable them to implement adequate diagnostic and therapeutic interventions, thereby achieving good outcomes after kidney transplantation." (PMID 26380104, 2015). "APRT deficiency and primary hyperoxaluria can pose a diagnostic challenge to transplant nephrologists in two situations." (PMID 26380104, 2015). "We believe that the possibility of APRT deficiency or primary hyperoxaluria should be questioned in all ESRD patients with a history of urolithiasis unless the nature of the nephropathy and kidney stones has been unambiguously established elsewhere." (PMID 26380104, 2015). "Adenine phosphoribosyl transferase (APRT) deficiency and primary hyperoxaluria are rare inborn errors of human metabolism." (PMID 26380104, 2015). "In addition, genetic disorders such as primary hyperoxaluria, cystinuria, adenine phosphoribosyltransferase (APRT) deficiency, 2,8-dihydroxyadeninuria, and Lesch–Nyhan syndrome can be diagnosed as the cause of recurrent urinary tract stone disease." (PMID 39273579, 2024). "These patients should be investigated for APRT deficiency and primary hyperoxaluria." (PMID 26380104, 2015). "These include cystinuria, primary hyperoxaluria, distal renal tubular acidosis (RTA), xanthinuria, Lesch–Nyhan syndrome, Dent disease, and adenine phosphoribosyltransferase (APRT) deficiency (a cause of dihydroxyadenine stones)." (PMID 36766999, 2023). "In patients with CKD, APRT deficiency and primary hyperoxaluria are frequently misdiagnosed as non-genetic kidney stones, chronic interstitial nephritis, obstructive nephropathy or hypertensive nephrosclerosis." (PMID 26380104, 2015).
urolithiasis (5 papers, 2009 to 2025). Stone(s) within the urinary tract. "APRT deficiency can have varied presentations, ranging from asymptomatic to recurrent urolithiasis to massive precipitation of DHA crystals in the kidneys." (PMID 40182129, 2025). "The commonest clinical manifestation of APRT deficiency is urolithiasis, and this is the first presentation in 54-73% of cases." (PMID 41383865, 2025).
leukaemia (3 papers, 2017 to 2024). "APRT (Adenine Phosphoribosyltransferase) has the potential to be a target for cancer treatment, as suppressing the APRT gene has harmful effects on leukemia cell lines." (PMID 38970097, 2024). "APRT, a human metabolic enzyme, can lead to a significantly decreasing of leukaemia cell proliferating by inhibiting the synthesis of polyamines when it was knocked down." (PMID 32351780, 2020). "We focused on Adenine Phosphoribosyltransferase (APRT) and demonstrated the detrimental consequence of APRT gene silencing on different leukaemia cell lines." (PMID 29084986, 2017).
Nephropathy (3 papers, 2015 to 2023). A nonspecific term referring to disease or damage of the kidneys. "Recently, it was shown that TNFR-1 (TNF receptor 1) knockout mice were protected from 2,8-DHA nephropathy, suggesting that TNFR1 antagonism could be a potential future target for APRT deficiency in human." (PMID 32260098, 2020).
adenine phosphoribosyltransferase deficiency (2 papers, 2014 to 2015). Adenine phosphoribosyltransferase (APRT) deficiency is a rare autosomal recessive (AR) disorder characterized by the formation and hyperexcretion of 2,8-dihydroxyadenine (2,8-DHA) in urine, causing urolithiasis and crystalline nephropathy. "Adenine phosphoribosyltransferase deficiency (APRTD) is a rare autosomal recessive metabolic disorder due to a mutation of the APRT gene." (PMID 24986359, 2014).
end-stage renal disease (2 papers, 2019 to 2025). "We present two cases of APRT deficiency in two men with varying presentations and progression to end-stage renal failure." (PMID 41383865, 2025).
renal failure (2 papers, 2011 to 2021). "Notably, in Pt 2 with APRT deficiency, excessive production and renal excretion of 2,8-dihydroxyadenine was the key pathophysiology leading to the recurrent formation of renal stones and eventual renal insufficiency with tubular degeneration." (PMID 34217267, 2021).
acute leukemia (1 paper, 2017). A clonal (malignant) hematopoietic disorder with an acute onset, affecting the bone marrow and the peripheral blood. "In order to provide further insights into the nature of APRT as essential gene, we extended the analysis and conducted a more detailed in vitro silencing in several acute leukemia cell lines: CEMO-1, KG-1 (Acute myeloid leukemia (AML)), PEER, MOLT-4 (T-ALL), and MY (B-ALL)." (PMID 29084986, 2017).
Allergy (1 paper, 2022). An allergy is an immune response or reaction to substances that are usually not harmful. "This protein group includes proteins involved in cell stress response (HSPB1), mucosal protection and allergy (MUC1), complement activation (CD55) and actin polymerization (CAPG, APRT, TPPP3)." (PMID 35590254, 2022).
atherosclerosis (1 paper, 2025). A disease characterized by the build-up of fatty material and calcium deposition in the arterial wall resulting in partial or complete occlusion of the arterial lumen. "Notably, current research on APRT has predominantly focused on the relationship between APRT deficiency and childhood renal dysfunction, while studies on LCAT have primarily centered on its cardioprotective effects in male populations with atherosclerosis." (PMID 40927188, 2025).
glioblastoma multiforme (1 paper, 2025). "Moreover, the inhibition of METTL3 can increase glioblastoma stem cell self-renewal by modulating m6A modification of adenine phosphoribosyltransferase (APNG) mRNAs, thereby increasing the sensitivity of glioblastoma multiforme to temozolomide." (PMID 40986143, 2025).
glioma (1 paper, 2021). A benign or malignant brain and spinal cord tumor that arises from glial cells (astrocytes, oligodendrocytes, ependymal cells). "The gene expression levels of H6PD, G6PD, ADSL, APRT, GMPS, PRPS1, and IMPDH1 in human glioma patients were significantly higher than those in the control group." (PMID 33723244, 2021).
hepatocellular carcinoma (1 paper, 2012). A malignant tumor that arises from hepatocytes. "Adenine phosphoribosyltransferase is an enzyme involved in the purine nucleotide salvage pathway, which is up-regulated in hepatocellular carcinoma and has been associated with Wnt/β-catenin activation." (PMID 22506042, 2012).
immune deficiency (1 paper, 2025). "In the process of GSEA results of the four diagnostic genes (APRT, ARG1, UMPS, and LDHB) suggested that these four diagnostic genes were mainly enriched in mitochondrial gene expression, primary immune deficiency, other energy metabolism-related functions, and immune-related pathways." (PMID 40774030, 2025).
lymph node metastasis (1 paper, 2025). "ADSL, ADCY3, and NME6 were associated with lymph node metastasis, distant metastasis, and differentiation, whereas APRT and NME3 were independent of these clinical variables." (PMID 40017120, 2025).
melanoma (1 paper, 2014). A malignant, usually aggressive tumor composed of atypical, neoplastic melanocytes. "In line with this, we found increased expression of the key enzymes of nucleotide salvaging HGPRT (HPRT1), thymidine kinase (TK1) and APRT in melanoma (primary and metastatic) compared to normal skin and benign nevi." (PMID 24941944, 2014).
prostate carcinoma (1 paper, 2024). A carcinoma that arises from epithelial cells of the prostate gland. "The identification of potential biomarkers such as APRT, CCL2, BEX2, MGC26963, and PLAU through specific gene modules and key genes could enhance our perception of prostate cancer's molecular mechanisms and targeted treatments." (PMID 38970097, 2024).
Sepsis (1 paper, 2025). Sepsis is defined as life-threatening organ dysfunction caused by a dysregulated host response to infection. "Consistent clustering of Sepsis samples in GSE65682 dataset was conducted based on four diagnostic genes (APRT, ARG1, UMPS, LDHB) associated with patient survival." (PMID 40774030, 2025). "•Identified 4 diagnostic genes (APRT, ARG1, UMPS and LDHB) for sepsis prognosis." (PMID 40774030, 2025). "Four diagnostic genes (APRT, ARG1, UMPS and LDHB) with excellent diagnostic value were identified, which might be mainly concentrated in energy metabolism-related functions and the immune-related pathway in the Sepsis process." (PMID 40774030, 2025). "APRT, ARG1, UMPS, and LDHB might be new ideas for studies related to the diagnosis and treatment of Sepsis." (PMID 40774030, 2025).
cancer (9 papers, 2017 to 2025). A tumor composed of atypical neoplastic, often pleomorphic cells that invade other tissues. "Adenine phosphoribosyltransferase (APRT) is a metabolic enzyme that participates in the production of polyamines, which are essential for the rapid growth of cancer cells." (PMID 38970097, 2024). "Genes such as APRT, CCL2, BEX2, MGC26963, and PLAU were identified as key genes significantly associated with cancer progression." (PMID 38970097, 2024). "On the other hand, the role of APRT in cancer is poorly understood and constitutes an attractive target to be explored." (PMID 29084986, 2017). "The differential gene expression profile between cancer cells sensitive or resistant to APRT silencing provided a molecular scenario that could contribute to clarify this cell-specific essentiality." (PMID 29084986, 2017). "In this study, we focused on the identification of genetic perturbations that hamper polyamine production and propose Adenine Phosphoribosyltransferase (APRT) as a candidate target to inhibit the production of these biomolecules and, in turn, curb cancer cell growth." (PMID 29084986, 2017). "This is shown in our study, where APRT could be a cancer-specific target, given that cancer cells exhibit a higher dependence on polyamines over healthy cells." (PMID 29084986, 2017). "We systematically addressed the existence of a correlation between the expression levels of APRT, HPRT1, XDH in the 60 human cancer cell lines and their pattern of drug sensitivity." (PMID 30104401, 2018). "APRT catalyses a salvage reaction and the recycling of adenine into AMP, thus limiting the need for de novo synthesis of purines by cancer cells." (PMID 30104401, 2018). "Notably, we previously showed that top genes of this program (LDHB, GSTK1, DGKA, APRT, MGAT4A, and NMRK1) are predictive of the response of patients with cancer to ICIs." (PMID 40187353, 2025). "APRT increases AMP levels, activating AMPK, which inhibits cancer growth." (PMID 40017120, 2025). "So far, APRT and GALNS have not been described in connection with cancer or cancer‐associated molecular pathways." (PMID 30259648, 2018).
kidney disease (6 papers, 2015 to 2025). "In recent years, the research on APRT has mainly focused on the relationship between APRT deficiency and kidney disease." (PMID 40927188, 2025). "The mechanism of adenine-induced kidney disease has not been established, although it has been postulated that conversion of adenine to 2,8-dihydroxyadenine is a driver of CKD in patients with mutations of adenine phosphoribosyltransferase (APRT), the major enzyme that metabolizes adenine to AMP." (PMID 37616058, 2023).
tumor (6 papers, 2012 to 2025). "Adenine is phosphoribosylated by adenine phosphoribosyltransferase to form AMP, thus competitively inhibiting phosphoribosylation of 6-TG to a toxic nucleotide, and protecting normal cells while killing MTAP-deficient tumor cells." (PMID 31284411, 2019). "Interestingly, expression levels of APRT also showed great inter-tumour heterogeneity, yet to a smaller extent than XDH (a more than 102-fold difference between the median expression values in the high compared with low-expressing tumour types)." (PMID 30104401, 2018). "We suggest that tumour cells that produce less UA as a consequence of increased APRT activity and purine salvage, might be more sensitive to 5-FU." (PMID 30104401, 2018). "In addition, proteomic analysis of spots isolated from 2D gels revealed some proteins also found in 1D gel, such as cyclophilin A, adenine phosphoribosyltransferase, translationally controlled tumor protein and heat-shock cognate 71 kDa protein." (PMID 29215607, 2017). "Our study highlights APRT, in addition to XDH, as a source of individual variability in uricogenesis among tumours." (PMID 30104401, 2018). "In agreement with our data, cells sensitive to APRT-silencing present a low APRT/SRM ratio, suggesting that they are prone to DHA production and tumor suppression upon APRT perturbation." (PMID 29084986, 2017).
infection (2 papers, 2010 to 2019). The state of being infected such as from the introduction of a foreign agent such as serum, vaccine, antigenic substance or organism. "Amido ribosyltransferase (AMPRT), which commits pentose phosphate pathway metabolite PRPP to nucleotide biosynthesis, had increased mRNA abundance but there were lowered transcript levels for adenine phosphoribosyltransferase (APRT) at 24 hours post infection." (PMID 20731870, 2010). "Apart from proteins discussed in more detail below, other accumulated proteins upon infection included galectin 1 and macrophage-capping protein, and less abundant endoplasmin, GTP-binding nuclear protein RAN, peptidyl-prolyl cis-trans isomerase FKBP4, and adenine phosphoribosyltransferase." (PMID 31708904, 2019).
metabolic disorder (1 paper, 2022). "This systematic review aimed to provide a valuable overview of this rare inherited metabolic disorder in the context of kidney transplantation, emphasizing the need for a comprehensive understanding on APRT deficiency among all the healthcare stakeholders." (PMID 35635787, 2022).
APRT also shares sentences with these, for which no sentence is quoted: cystinuria (4 papers); chronic kidney disease (3); Dent disease (3); acute renal failure (2); distal renal tubular acidosis (2); genetic disorders (2); interstitial nephritis (2); kidney failure (2); Lesch-Nyhan syndrome (2); xanthinuria (2); acute myeloid leukemia (1); Fabry disease (1); fibromuscular dysplasia (1); glomerulonephritis (1); Huntington disease (1); Insulin resistance (1); mastitis (1); mitochondrial DNA depletion syndrome (1); Parkinson disease (1); primary hyperparathyroidism (1); Pure red cell aplasia (1); renal dysfunction (1); renal fibrosis (1); Sjögren's syndrome (1); type 2 diabetes (1).